POLG (DNA polymerase gamma, catalytic subunit)
Diseases named in the same sentence as POLG in open-access papers (continued):
Sharing a sentence is not in itself a finding about the gene and the disease.
epilepsy (continued). "In the group analyzed with the epilepsy panel, the most variations were detected in the POLG gene (in seven patients, including five males and two females)." (PMID 40565516, 2025). "In the adult PMD cohort, two of five patients with bi-allelic POLG-related disease and eight of ten patients with mtDNA disease had epilepsy." (PMID 40445405, 2025). "These diets have shown effectiveness in controlling epilepsy, improving eye movements, and supporting mental development in patients with mutations in genes such as ECHS1, POLG, TMEM126B, and PDHA 1, which causes pyruvate dehydrogenase deficiency." (PMID 40149709, 2025). "Using epilepsy panels and WES, we identified rare variants in several genes, including POLG, SCN1A, SCN9A, KIF1A, and CNTNAP2, which were associated with specific clinical characteristics." (PMID 40565516, 2025). "The review of published cases has allowed us to identify and summarize the epileptic phenotype of POLG-related epilepsy, particularly focusing on the age at onset, seizure type and outcome." (PMID 33113942, 2020). "Only one study has investigated cognition in patients with POLG‐related mitochondrial disease (N:8; mitochondrial spinocerebellar ataxia and epilepsy phenotype)." (PMID 31448495, 2020). "This work focuses on the epilepsy as a feature of POLG-related disease, highlighting the spectrum of epilepsy phenotypes, clinical recognition, and treatment options." (PMID 28837072, 2017). "Lastly, the exclusion of gene mutations associated with fever-sensitive epilepsies, such as the SCN1A gene coding for the DNA polymerase subunit gamma-1 (POLG-1) and the protocadherin 19 (PCDH19) gene, may aid the diagnosis of FIRES." (PMID 41462849, 2025). "The pathological mechanisms underpinning epilepsy in POLG-related disease remain obscure." (PMID 37259148, 2023). "However, delineating the exact pathophysiological role of astrocytes in Alpers’ syndrome is critical to better understand the specific mechanisms underpinning POLG-related epilepsy." (PMID 37259148, 2023). "The patient (Proband No. 25) with POLG missense variant had optic atrophy since the age of 8 years, along with epilepsy." (PMID 34573359, 2021). "The highest levels were detected in two patients with POLG mutations (85252 pg/mL and 13215 pg/mL) followed by P4 of this study carrying TK2 mutations (8000 pg/mL) and a patient with lactic acidosis and epilepsy bearing the mtDNA A3243G mutation (P12), (6999 pg/mL)." (PMID 24484525, 2014). "Mutations in POLG coding for a mitochondrial DNA-polymerase are classically associated with Alpers syndrome but are also present in mitochondrial recessive ataxia syndrome (MIRAS), spinocerebellar ataxia with epilepsy (SCAE), and myoclonus, epilepsy, myopathy, sensory ataxia (MEMSA) syndrome." (PMID 33918863, 2021). "We found that the minimum prevalence of the three most common POLG mutations either as homozygous or compound heterozygous state was 2.3% among a prospective cohort of 213 children with intractable epilepsy without liver manifestation at presentation of epilepsy." (PMID 23448099, 2013). "The aim of this study was to assess prospectively the prevalence of the three most common POLG mutations in a defined population of children with nonsyndromic intractable epilepsy, but without liver manifestation typical for Alpers disease at the presentation of their epilepsy." (PMID 23448099, 2013).
Alpers syndrome (35 papers, 2011 to 2025). A cerebral degeneration that results in progressive degeneration of grey matter in the cerebrum and has_symptom convulsions. "In our research, we converted fibroblasts from an Alpers' syndrome patient with POLG mutations into iPSCs, and then into NSCs and 3D cortical organoids." (PMID 38385069, 2024). "Historical patients (†) remain without a molecular diagnosis since they precede identification of pathogenic POLG variants known to cause Alpers’ syndrome and extraction of DNA from FFPE tissues to sequence POLG was unsuccessful." (PMID 37259148, 2023). "The patient cohort consisted of ten patients with clinically- and neuropathologically-defined Alpers’ syndrome, including three patients with confirmed bi-allelic pathogenic variants in POLG, and three adult patients with POLG-related encephalopathy." (PMID 37259148, 2023). "Refractory epilepsy is the main neurological manifestation of Alpers’ syndrome, a severe childhood-onset mitochondrial disease caused by bi-allelic pathogenic variants in the mitochondrial DNA (mtDNA) polymerase gamma gene (POLG)." (PMID 37259148, 2023). "A further significant limitation was that only patients with pathogenic POLG variants diagnosed with Alpers–Huttenlocher syndrome or Alpers syndrome were included, where liver impairment is part of the disease pathogeneses." (PMID 36142570, 2022). "Alpers' syndrome is a severe neurodegenerative disease typically caused by bi‐allelic variants in the mitochondrial DNA (mtDNA) polymerase gene, POLG, leading to mtDNA depletion." (PMID 35790454, 2022). "Alpers' syndrome is predominantly caused by bi‐allelic pathogenic variants in POLG, which encodes the catalytic subunit of DNA polymerase gamma." (PMID 35790454, 2022). "Genetic testing revealed Alpers syndrome with POLG mutation in 3 (37.5%) patients and a SCN2A-mutation in 1 (12.5%) patient." (PMID 34149600, 2021). "Alpers’ syndrome is one of the most serious phenotypes of mitochondrial disease caused by POLG gene mutation." (PMID 34690748, 2021). "Mutations in POLG can cause among others the neurological conditions Alpers syndrome and progressive external ophthalmoplegia (PEO), and the latter can associate with POI." (PMID 34803902, 2021). "A notable developmental delay with the signs of POLG mutation was found in all patients who suffered from Alpers’ syndrome in life." (PMID 34690748, 2021). "The Alpers’ syndrome caused by POLG gene mutations usually affects children aged less than 4 years, and inevitably leads to death." (PMID 34690748, 2021). "Alpers syndrome is a severe pediatric encephalopathy associated with liver failure, due to recessive POLG mutations." (PMID 33802970, 2021). "Alpers’ syndrome is a rare mitochondrial encephalopathy, which is thought to be caused by autosomal recessive mutations in the nuclear-encoded catalytic subunit of POLG." (PMID 34690748, 2021). "The occipital lobe appears to be the main site for seizure genesis in Alpers’ syndrome and visual disturbances are also frequently described in both paediatric and adult patients harboring POLG mutations." (PMID 30021052, 2019). "Mutations S305R and P1073L in the POLG gene have been reported to be associated with early childhood Alpers syndrome." (PMID 25914719, 2015). "As it is often the case for the severe recessive mitochondrial disorders caused by POLG mutations (like the Alpers syndrome), the affected individuals are compound heterozygotes." (PMID 26077851, 2015). "The A467T mutation has been found in all of the major POLG related diseases, i.e. Alpers syndrome, ataxia-neuropathy syndromes and PEO." (PMID 22125488, 2011). "We characterise a novel splice site mutation in POLG found in trans with the p.A467T mutation in a 3.5 years old boy with valproic acid induced acute liver failure (Alpers-Huttenlocher syndrome)." (PMID 21235791, 2011). "More than 90% of Alpers' syndrome cases are linked to mutations in the POLG gene." (PMID 38385069, 2024).
Alpers syndrome (continued). "Alpers' syndrome is an early-onset neurodegenerative disorder usually caused by biallelic pathogenic variants in the gene encoding the catalytic subunit of polymerase-gamma (POLG), which is essential for mitochondrial DNA (mtDNA) replication." (PMID 38385069, 2024). "In terms of therapy, whereas valproate is contraindicated in other mitochondrial encephalopathies, such as Alpers syndrome due to pathogenic variants in POLG (DNA polymerase γ), as it can lead to fulminant liver failure, there are no definite data on valproate toxicity in PARS2‐related DEE." (PMID 38087948, 2024). "Furthermore, due to the rarity of Alpers’ syndrome, access to post-mortem brain tissues from patients with confirmed bi-allelic pathogenic variants in POLG were limited." (PMID 37259148, 2023). "All 22 patients (100%) with POLG mutation-related Alpers’ syndrome experienced epileptic seizures." (PMID 34690748, 2021). "The clinical characteristics of POLG mutation-related Alpers’ syndrome were analyzed as follows." (PMID 34690748, 2021). "Alpers’ syndrome is an early‐onset neurodegenerative disorder often caused by biallelic pathogenic variants in the gene encoding the catalytic subunit of polymerase‐gamma (POLG) which is essential for mitochondrial DNA (mtDNA) replication." (PMID 30021052, 2019). "The causal link between POLG mutations and Alpers syndrome was first reported in 2004." (PMID 28837072, 2017). "The fact that organ and CNS tissues are most affected in homozygous animals is compelling, given that liver dysfunction, along with intractable seizures, is the hallmark of the liver-CNS disease known as Alpers syndrome, the main childhood mitochondrial disease caused by POLG mutations." (PMID 26519465, 2015). "Furthermore, detection of the primary mutations in POLG did not only confirm the clinical diagnosis of Alpers syndrome, but also allowed a reliable prenatal diagnosis for the parents in the following pregnancy." (PMID 21235791, 2011). "Although, to date, this remains the largest post-mortem PMD neuropathological study, due to the rarity of Alpers’ syndrome, we included historical post-mortem tissues from patients that preceded the genetic discovery of POLG-related PMD." (PMID 40445405, 2025). "Mitochondrial mass within the granular cell layer was significantly higher in patients with Alpers’ syndrome compared to controls (P = 0.0344), whereas mitochondrial mass remained unaltered in the late-POLG and mtDNA disease patient groups." (PMID 40445405, 2025). "Quantification of the density of Purkinje cells in control and PMD patient tissues revealed a significantly decreased abundance of Purkinje cells (P < 0.05) in the Alpers’ syndrome, late-POLG and mtDNA disease patient groups relative to age-matched controls." (PMID 40445405, 2025). "Crucially, our findings provide further evidence of occipital lobe involvement in Alpers’ syndrome and support the involvement of reactive astrocytes in the pathogenesis of POLG-related disease." (PMID 37259148, 2023). "Since astrocytes appear to exhibit a pathological phenotype in post-mortem brain tissues from patients with Alpers’ syndrome, it is critical changes to astrocytic functions are interrogated in model systems of POLG-related pathology." (PMID 37259148, 2023). "To determine the involvement of astrocytes in the pathophysiology of Alpers’ syndrome and POLG-related disease, we sought to phenotypically characterise reactive astrocytes within occipital cortex tissues." (PMID 37259148, 2023). "We investigated a postmortem cohort of eight patients with clinically and neuropathologically defined Alpers' syndrome and six patients with genetically confirmed Alpers' syndrome and POLG‐related encephalopathy." (PMID 35790454, 2022). "For the analysis of POLG-related Alpers’ syndrome, 22 out of 29 patients were included (8 females, 14 males, The median age at onset was 2.33 years, the range of age-onset was from 2 months to 17 years)." (PMID 34690748, 2021).
Alpers syndrome (continued). "In humans, mutations in POLG cause many mitochondrial pathologies, like PEO, Alpers' syndrome and ataxia-neuropathy syndrome." (PMID 25852747, 2015). "In Alpers syndrome, the identified pol γ mutations are either homozygous A467T (MIM 174763.0002) or heterozygous A467T paired in trans with other mutations in POLG." (PMID 22125488, 2011). "In this paper we describe the molecular genetic analysis of POLG in a 3.5 years old boy with VPA induced fatal liver failure (Alpers-Huttenlocher syndrome, AHS)." (PMID 21235791, 2011). "Qualitative assessment of cerebellar tissues revealed visibly more severe atrophy of the cerebellar cortex in patients with Alpers’ syndrome relative to age-matched controls, in comparison to adult patients with POLG-related disease and mtDNA disease relative to adult controls." (PMID 40445405, 2025). "Still, in some patients, this effect was only temporary, and in the case of Alpers syndrome (pathogenic variant in POLG), KD did not improve prognosis as relates to survival." (PMID 38542723, 2024). "There are certain differences in the clinical phenotype of Alpers’ syndrome caused by POLG gene mutations and NON-POLG gene mutations." (PMID 34690748, 2021). "The frequency of this adverse effect is very high in patients with Alpers' syndrome bearing mutations in POLG, and also in subjects not affected by Alpers' syndrome but carrying Pol γ polymorphisms." (PMID 25852747, 2015). "Pathogenic mutations in POLG have been identified in patients with neurological or muscular diseases including progressive external ophthalmoplegia (PEO), Alpers syndrome, ataxia-neuropathy syndromes, idiopathic parkinsonism, and nucleoside reverse-transcriptase inhibitor (NRTI) toxicity." (PMID 22125488, 2011). "In patients with Alpers’ syndrome, increased protein expression of c-Fos, a gene transiently expressed as an early response to neuronal activity, was observed relative to patients with late-POLG and mtDNA PMD, indicating hyperexcitability in subregions of the cerebellar cortex." (PMID 40445405, 2025). "In addition, clinicians should keep in mind that there are mitochondrial syndromes and phenotypes resulting from nDNA pathogenic variants, such as variants in the POLG and TWNK genes responsible for Alpers syndrome and Autosomal Dominant Progressive External Ophthalmoplegia, respectively." (PMID 36859275, 2023). "For these reasons, we sought to identify whether astrocytes in Alpers’ syndrome and POLG-related disease manifest morphological changes, mitochondrial OXPHOS protein deficits, and/or alterations to glutamate metabolism and ionic homeostasis that could contribute to the neurological phenotype." (PMID 37259148, 2023). "Similarly, she did not have the common pathogenic POLG variants associated with Alpers' syndrome." (PMID 29575569, 2018).
progressive external ophthalmoplegia (23 papers, 2010 to 2025). A mitochondrial myopathy characterized by slowly progressive paralysis of the levator palpebrae, orbicularis oculi, and extraocular muscles. "The mutant lines were homozygous either for PolɣAV1106A or for the PolɣAY955C mutation that is the most common autosomal dominant mutation in POLG and a cause of progressive external ophthalmoplegia (PEO)." (PMID 39918244, 2025). "Mutations in POLG are responsible for progressive external ophthalmoplegia, which includes cataracts as an additional symptom." (PMID 34059112, 2021). "Notably, our results showed two variants on the POLG gene, both in the same patient, which the literature has currently associated with progressive external ophthalmoplegia (PEO)." (PMID 38137339, 2023). "However, the clinical consequences of this complex allele need to be further clarified because heterozygous POLG mutations have been associated with an autosomal dominant form of progressive external ophthalmoplegia (adPEO)." (PMID 35330074, 2022). "Recently, mutations in the catalytic subunit of mitochondrial DNA polymerase gamma (POLG) were shown to segregate with POI in families with progressive external ophthalmoplegia (PEO) and multiple large-scale rearrangements of mitochondrial DNA (mtDNA)." (PMID 38649916, 2024). "Among nuclear DNA-related cases, mutations in POLG and POLG2, which encode subunits of mitochondrial DNA polymerase γ, are particularly significant, causing conditions such as Alpers-Huttenlocher syndrome and progressive external ophthalmoplegia." (PMID 41453949, 2025). "Besides, several reports have demonstrated that various POLG mutations are associated with mtDNA-deletion-related diseases, including sensory ataxic neuropathy, dysarthria and ophthalmoparesis (SANDO), and progressive external ophthalmoplegia (PEO)." (PMID 33671400, 2021).